INS (insulin)
Diseases named in the same sentence as INS in open-access papers (continued):
Sharing a sentence is not in itself a finding about the gene and the disease.
diabetes (continued). "Among them, 24 participants were excluded based on the predefined exclusion criteria, including diabetes mellitus (n = 6), thyroid disorders (n = 5), recent use of hormonal or insulin-sensitizing medications (n = 7), and other causes of hyperandrogenism or ovulatory dysfunction (n = 6)." (PMID 41515662, 2026). "Furthermore, AD and FTD risks are abetted by obesity/diabetes-induced hyperinsulinemia and hyperactivation of brain insulin signaling, and progranulin deficiency activates insulin signaling in fat and liver." (PMID 42095076, 2026). "However, as the patient ages, the phenotype “flips” from insulin excess to insulin deficiency, eventually leading to the development of diabetes mellitus in childhood or early adulthood." (PMID 41614934, 2026). "We hypothesized that distinct insulin‐derived mechanisms and lipid profiles discriminate sex differences and can be used to identify subjects at higher risk to develop diabetes‐related complications." (PMID 41133433, 2026). "Additionally, the water extract of S. grosvenorii enhances the pancreas’s ability to secrete insulin in a fasting state, resists oxidative stress caused by diabetes, and slows down kidney damage induced by diabetes." (PMID 41584700, 2026). "The prevalence of rheumatoid arthritis is closely associated with diabetes as elevated levels of insulin are found in RA patients and may induce nephropathy due to immune‐mediated kidney damage." (PMID 41561890, 2026). "Structured health education, insulin therapy for blood glucose control, and advanced digital treatments can enhance the patient experience, suggesting that treatment satisfaction is linked to diabetes knowledge." (PMID 41311517, 2026). "For example, experimental studies that suppressed N3, without changing the total amount of sleep, observed significantly increased blood pressure and reduced insulin sensitivity and glucose tolerance, and these changes are risk factors for the development of hypertension and diabetes." (PMID 40817294, 2025). "Developing a regenerative therapy that can expand pancreatic β-cell mass, boost endogenous insulin production, and restore glucose homeostasis presents a transformative opportunity for diabetes treatment, where β-cell loss is a contributing factor to disease progression." (PMID 40885390, 2025). "Indeed, carriers of these variants (Asp563Gly and Ser539Trp) experience a clinical syndrome characterized by impaired insulin secretion, thereby increasing the risk of developing overt diabetes." (PMID 39137152, 2025). "Some genes, like the INS gene, are reported to have mutations that lead to the production of structurally abnormal INS with reduced biological activity and receptor binding that causes diabetes mellitus." (PMID 41376825, 2025). "Another notable mechanism through which harmal-e-shami contributes to diabetes management is its influence on adiponectin levels, a hormone closely associated with improved insulin sensitivity, further emphasizing its potential therapeutic role in glycemic control." (PMID 41007291, 2025). "Therefore, diabetes patients require education about temperature variations and the appropriate duration of storing insulin pens to maintain the insulin potency (American Association of Diabetes Educators, 2020)." (PMID 40376558, 2025). "Additionally, insulin use, particularly in advanced diabetes, has been associated with an increased infection risk, possibly due to impaired immune function and delayed healing." (PMID 40072731, 2025). "However, when these cells become dysfunctional—either through impaired insulin secretion, loss of β-cell mass, or both—this regulation fails, resulting in chronic hyperglycemia, the hallmark of diabetes mellitus." (PMID 40732992, 2025).
diabetes (continued). "Type 1 diabetes mellitus (T1DM) results from autoimmune-mediated destruction of pancreatic beta-cells leading to absolute insulin deficiency, while Type 2 diabetes mellitus (T2DM) arises from a complex interplay of insulin resistance and progressive beta-cell dysfunction." (PMID 41180185, 2025). "By lowering these inflammatory markers, the consumption of BGNF may reduce the overall inflammatory burden, improve insulin sensitivity, and minimize the risk of diabetes complications." (PMID 40026940, 2025). "The chronic elevation of fractalkine (CX3CL1) from adipose tissue is associated with inflammation and insulin resistance, suggesting that exercise may counteract the inflammatory pathways linked to metabolic dysfunction in diabetes." (PMID 40091956, 2025). "Additionally, LCDs were associated with significant reductions in diabetes medication use, highlighting their potential to decrease pharmacological dependency and improve metabolic outcomes, including enhanced insulin sensitivity and reduced inflammation." (PMID 39912024, 2025). "Ethnic variations in genes related to lipid metabolism and insulin sensitivity could modulate the relationship between the TyG-i and diabetes risk." (PMID 40917348, 2025). "Islet cell transplantation is regarded as a promising treatment for insulin-deficient diabetes." (PMID 40806765, 2025). "Additionally, a decrease in insulin sensitivity followed by a subsequent decrease in β-cell function according to the time of onset was related to the risk of diabetes." (PMID 40361840, 2025). "Notably, many PDAC patients develop new-onset diabetes as an early symptom, likely due to the disruption of insulin secretion caused by tumor growth." (PMID 39948335, 2025). "Diabetes is a chronic metabolic disorder characterized by elevated blood glucose levels, also known as hyperglycemia, which stems from a deficiency in insulin secretion, insulin action, or both." (PMID 39857806, 2025). "INS variants caused monogenic diabetes in a heterogeneous group of patients." (PMID 40303944, 2025). "Importantly, PA also confers broad systemic benefits by lowering cardiovascular risk, improving insulin sensitivity, and supporting weight management, factors particularly relevant to patients with diabetes who frequently present with multimorbidity." (PMID 41267734, 2025). "Defective insulin secretion is a hallmark of diabetes mellitus." (PMID 40161790, 2025). "Moreover, the review explores the roles of genes that contribute to beta-cell dysfunction, impaired insulin secretion, and vascular complications associated with diabetes, offering insights into their genetic and epigenetic mechanisms." (PMID 40149950, 2025). "Diabetes mellitus (DM) is a metabolic disorder arising from a combination of genetic and environmental factors, primarily characterized by either an absolute or relative deficiency in insulin secretion as well as decreased sensitivity to insulin action." (PMID 40474981, 2025). "The JNK pathway regulates insulin production and has been implicated in Drosophila diabetes." (PMID 39940855, 2025). "It is essential that these investigations consider that diabetes can be caused by a variety of factors, including genetic factors, alterations in insulin production or action, as well as environmental influences and lifestyles that contribute to metabolic dysfunction." (PMID 41154485, 2025). "In consistent with this review a large survey in UK, find that infection was identified as the most common precipitating factor for diabetic ketoacidosis (45%), followed by insulin omission (20%); other causes included newly diagnosed diabetes and alcohol or drug related problems." (PMID 39903717, 2025). "Therefore, this cPLA2-mediated abnormal signaling cascade is a hallmark of impaired insulin sensitivity, linking metabolic and neurodegenerative disorders and reinforcing the connection between AD and diabetes." (PMID 41280311, 2025).
diabetes (continued). "Additionally, pollution–induced inflammation and oxidative stress can impair insulin sensitivity, increasing the risk of diabetes." (PMID 40265163, 2025). "It is likely that altered fatty acid composition mediates the impact of desaturase activity on diabetes risk, as membrane lipid content may influence insulin signaling, receptor binding, and function." (PMID 40362254, 2025). "For example, patients with diabetes using AI-controlled insulin pumps may face an increased risk of hypoglycemia if the system cannot adjust insulin dosage based on physical activity levels." (PMID 41469989, 2025). "We also found that use of insulin was strongly associated with diabetes distress." (PMID 39972441, 2025). "Studies have demonstrated that polydatin can enhance glucose metabolism and uptake while simultaneously decreasing lipid accumulation in insulin-resistant human hepatoma HepG2 cells, indicating its potential as a therapeutic agent in managing metabolic dysfunctions associated with diabetes." (PMID 40958722, 2025). "Type 1 diabetes mellitus (T1D) is a chronic autoimmune disease caused by the immune-mediated destruction of insulin-producing pancreatic beta cells, resulting in the lifelong need for exogenous insulin." (PMID 40004833, 2025). "C-peptide, which is released alongside insulin in equal quantities, acts as a reliable indicator of how well the beta cells of the pancreas are functioning and may be associated with diabetes-related complications." (PMID 41185830, 2025). "Other identified risk factors included longer diabetes duration (HR = 1.021; 95% CI = 1.008–1.033), poor glycaemic control (HR = 1.264; 95% CI = 1.096–1.458), insulin use (HR = 1.458; 95% CI = 1.192–1.784), and a smaller PAVR in 2017 (HR = 0.191; 95% CI = 0.070–0.518)." (PMID 41343177, 2025). "This narrative review describes the mechanisms of action, and the perioperative risks associated with each class of non-insulin diabetes medicines, so that practitioners can apply first principles for a rationale for the perioperative management of the non-insulin diabetes medicines." (PMID 40651878, 2025). "Annual reviews of frail older people with diabetes should include identification of risk factors of hypoglycaemia such as polypharmacy, impaired organ function, multiple comorbidities, especially cognitive dysfunction, and SU or insulin therapy." (PMID 40863223, 2025). "Diabetes mellitus is a common metabolic disorder with multiple causes, characterized by hyperglycemia and disruptions in carbohydrate, fat, and protein metabolism due to impaired insulin secretion or resistance to insulin action." (PMID 41333960, 2025). "Type 1 diabetes mellitus is a chronic autoimmune disease characterized by the destruction of pancreatic beta cells, leading to absolute insulin deficiency and lifelong dependence on exogenous insulin therapy." (PMID 41036118, 2025). "This could be explained by the hypoglycemic impact of QCT and SS through controlling enzymes responsible for glucose metabolism, modulating the functions of β-cells and insulin activity, and enhancing other parameters associated with diabetes." (PMID 39846548, 2025). "Insulin degrading enzyme (IDE) is a highly evolutionary conserved protease that has been involved in Insulin and amyloid-beta metabolism and consequentially associated to diabetes mellitus, metabolic syndrome, Alzheimer’s disease and amyloid angiopathy 34,35,36,37." (PMID 39866114, 2025). "Although some evidence suggests that vitamin D may improve insulin sensitivity and reduce the risk of diabetes, the overall findings are inconsistent." (PMID 40004770, 2025). "In T1D, adiponectin levels were reported to be about 30% higher than in healthy humans and associated positively with age and diabetes duration, but inversely with weight-adjusted daily insulin dose, BMI, and percentage trunk and visceral adipose tissue (VAT) volume." (PMID 39998445, 2025).
diabetes (continued). "Diabetes mellitus, a central metabolic disease associated with cardiovascular disease, stroke, hypertension, and deafness, is characterized by persistent hyperglycemia due to impaired insulin secretion, insulin resistance, or both." (PMID 41465450, 2025). "In diabetes, β-cell mitochondrial dysfunction arises from oxidative stress, impaired quality control and disrupted dynamics, leading to reduced oxidative phosphorylation, defective insulin release and progressive cell loss." (PMID 41369350, 2025). "This is an important aspect of insulin metabolism in maintaining glucose homeostasis, and improving beta-cell function is always desirable, especially for individuals who are at risk of or are managing diabetes." (PMID 40005307, 2025). "Recently, GLP1-RAs, a new anti-diabetic drug class causing insulin secretion through pancreatic cell stimulation, have been shown to prevent the development of diabetes in pre-diabetic subjects, to lower Hb1Ac and, importantly, to reduce gastric emptying and therefore encourage weight loss." (PMID 40682127, 2025). "Conversely, the postmenopausal decline in estrogen levels may result in diminished insulin sensitivity, increasing the susceptibility of women to diabetes." (PMID 40626240, 2025). "This may encompass microbes that influence blood sugar regulation, insulin sensitivity, and other metabolic processes associated with diabetes." (PMID 39852351, 2025). "In addition, we examined the baseline level and changes in β-cell function, insulin sensitivity indices, and the associated risk of diabetes during the period around menopause." (PMID 40361840, 2025). "The two main types of diabetes, type 1 (T1D) and type 2 diabetes (T2D), are classified on the bases of several parameters: age of onset, loss of β-cell function, insulin resistance, presence of autoantibodies associated with diabetes, and need for treatment with insulin." (PMID 41012462, 2025). "Furthermore, the strong statistical association (p < 0.0001) between thyroid dysfunction and insulin therapy likely identifies a patient subgroup with more advanced or difficult-to-control diabetes that warrants closer thyroid monitoring." (PMID 41306154, 2025). "Such a trend may reflect that the metabolic disturbances associated with insulin-treated diabetes may weaken the protective effects typically linked to higher BMI." (PMID 40967652, 2025). "LP was more effective than benazepril in lowering blood pressure and improving insulin sensitivity, which may contribute to a lower diabetes risk in hypertensive patients with IR." (PMID 40255834, 2025). "Their combined activity helps maintain β-cell integrity, modulate insulin dynamics, and protect the pancreas from metabolic injury, providing mechanistic insight into why Klotho deficiency contributes to impaired insulin secretion and diabetes progression." (PMID 41438297, 2025). "Meta-analyses of randomized controlled trials showed zinc supplementation improved glycemic control, insulin sensitivity, and reduced high-sensitivity C-reactive protein inflammatory marker in patients with diabetes and patients at high risk of developing diabetes." (PMID 40081495, 2025). "Vitamin D deficiency may impair insulin sensitivity and induce insulin resistance, thereby increasing the risk of diabetes." (PMID 41211221, 2025). "Studies have shown that preoperative insulin use is linked to lower rates of diabetes remission." (PMID 40740163, 2025). "While diabetes technology has rapidly improved over the past decade, lipodystrophy still represents a significant barrier to stable glycemic variability and increased risk of severe hypoglycemia by altering the absorption of insulin." (PMID 40003213, 2025). "Also, general information about diabetes (disease causes, diagnosis, symptoms, types, pancreas, and insulin) was an important item in the first component, a result that is consistent with other studies." (PMID 39961987, 2025).
diabetes (continued). "Type 2 Diabetes Mellitus (T2DM) is a chronic disease caused by the resistance of tissues to the actions of insulin as well as the progressive failure to produce adequate amounts of insulin in pancreatic β-cells." (PMID 41296415, 2025). "The development of insulin resistance precedes the occurrence of type 2 diabetes by several years; similarly, the loss of first-phase insulin secretory response to glucose challenge represents early evidence of pancreatic beta-cell defect that precedes the diagnosis of diabetes by several years." (PMID 40630937, 2025). "Additionally, genes such as TCF7L2 have been associated with glucose homeostasis and insulin signaling pathways, suggesting a potential role in the metabolic dysregulation observed in diabetes and its complications." (PMID 40692573, 2025). "Furthermore, regular exercise enhances insulin sensitivity, potentially reducing the risk of diabetes-related microvascular brain injury, which we also found to be a major risk factor in our cohort." (PMID 40648803, 2025). "Access to insulin and the duration of diabetes diagnosis were also linked to glucagon awareness." (PMID 40585626, 2025). "We previously demonstrated that elevated aminoadipic acid was associated with incident diabetes mellitus, and in the prodromal phase may be a compensatory mechanism to upregulate insulin secretion." (PMID 40463962, 2025). "Together, these factors improve insulin function, regulate blood sugar levels, reduce chronic inflammation, promote overall metabolic health and can considerably decrease the risk of developing diabetes." (PMID 39563945, 2025). "Interleukin 1β (IL-1β), is one of the important inflammatory markers associated with type-2 DM which in turn modifies β-cell apoptosis causing its damage subsequently affects insulin secretion, and suggestive that anti-inflammatory drugs can aid in diabetes management." (PMID 39820827, 2025). "Diabetes is a complex disease that can have autoimmune, genetic, or acquired causes, impairing the body’s ability to regulate blood sugar, often involving problems with insulin production, insulin action, or both." (PMID 41012898, 2025). "The DCCT (Diabetes Control and Complications Trial) and its long-term follow-up, the EDIC (Epidemiology of Diabetes Interventions and Complications) study, provide the strongest evidence that intensive insulin therapy significantly reduces the risk of long-term complications." (PMID 41142642, 2025). "The most representative terms are “non-insulin dependent diabetes mellitus” (1114), “risk factor”, “follow up”, “complication”, “glycosylated hemoglobin”, “disease duration”, “disease severity”, “glucose blood level”, “prognosis”, and “insulin”." (PMID 40283692, 2025). "There is evidence suggesting that oleanolic acid may improve inflammation and oxidative damage caused by diabetes since it improves the response to insulin." (PMID 40433407, 2025). "Diabetes is characterized by an insufficient function of pancreatic beta cells, leading to relative or absolute insulin deficiency, as well as to a reduced sensitivity of peripheral target tissues to insulin." (PMID 41303682, 2025). "The vast majority of diabetes cases are classified into two main etiopathogenetic types: type 1 diabetes (T1D), caused by a deficiency in β-cell function, and type 2 diabetes (T2D), resulting from insulin resistance and inadequate insulin secretion." (PMID 41141270, 2025). "To date, more than 90 INS gene mutations have been identified to cause diabetes in humans." (PMID 40392602, 2025). "Observational studies have indicated that zinc deficiency may impair insulin signaling, promote oxidative stress, and stimulate inflammatory signaling pathways, thereby increasing an individual’s susceptibility to diabetes." (PMID 41439937, 2025).